C2orf81 (chromosome 2 open reading frame 81)
Synonyms: LOC388963; hCG40743
Tractability: No criterion of Open Targets' tractability assessment is met for any kind of drug.
Gene: Protein-coding gene on chromosome 2 (74,414,176 to 74,421,619, reverse strand). Ensembl gene ENSG00000284308.
Subcellular location (Human Protein Atlas): Nucleoli; Nucleoli fibrillar center; Nucleoplasm
Genetic constraint (gnomAD): Loss-of-function variants: 5 observed, 7.28 expected, observed/expected ratio (o/e) 0.69, 90% interval 0.36 to 1.43. That is too few expected variants to judge how well the gene tolerates losing a copy. Missense variants: 781 observed, 825.02 expected, observed/expected ratio (o/e) 0.95, 90% interval 0.89 to 1. Synonymous variants: 346 observed, 365.99 expected, observed/expected ratio (o/e) 0.95, 90% interval 0.87 to 1.03.
Homologues: Orthologues: chimpanzee C2AH2orf81 (93% identical), macaque C13H2orf81 (92% identical), pig C2orf81 (65% identical), rabbit C2orf81 (60% identical), dog C2orf81 (57% identical), guinea pig C2orf81 (53% identical), mouse 1700003E16Rik (50% identical).